LRP8 (LDL receptor related protein 8)
Diseases named in the same sentence as LRP8 in open-access papers (continued):
Sharing a sentence is not in itself a finding about the gene and the disease.
endothelial dysfunction (6 papers, 2023 to 2025). In vascular diseases, endothelial dysfunction is a systemic pathological state of the endothelium (the inner lining of blood vessels) and can be broadly defined as an imbalance between vasodilating and vasoconstricting substances produced by (or acting on) the endothelium. "Future research should investigate the contribution of LRP8 signaling to endothelial dysfunction in SLE." (PMID 39234308, 2024). "Monocytes also release low-density lipoprotein receptor-related protein 8 (LRP8), which triggers vascular inflammation and endothelial dysfunction, further implicating them in the pathogenesis of AAD." (PMID 41035635, 2025). "Additionally, low-density lipoprotein receptor-related protein 8 (LRP8) is released from monocytes and can induce vascular inflammation and endothelial dysfunction, leading to AD." (PMID 37958896, 2023).
melanoma (6 papers, 2019 to 2025). A malignant, usually aggressive tumor composed of atypical, neoplastic melanocytes. "The LRP1 ligand ApoE is targeted by miR-199a-3p and -5p, and miR-1908 and the heat shock factor DNAJA4, suppressing LRP1 signaling on melanoma and LRP8 on endothelial cells." (PMID 36612285, 2022). "To investigate the premise of ApoE being a potent immune checkpoint, we challenged WT, apoE-/- and lrp8-/- mice with WT and ApoE knock out B16-F10 melanoma tumor cells." (PMID 36341364, 2022). "In murine models of melanoma, ApoE secreted by melanoma cancer cells suppressed tumor invasion and metastatic endothelial cell recruitment by binding to LRP1-positive melanoma cells and LRP8-positive endothelial cells." (PMID 33669052, 2021). "The effect of apoE seems to be at least partially mediated by its interaction with the Lrp8 receptor as this group also had slower tumor growth and rejection of tumor cells when apoE-/- melanoma cells were inoculated into Lrp8-/- mice, endorsing the in vitro findings in splenocyte studies." (PMID 36341364, 2022).
neuroblastoma (5 papers, 2022 to 2025). Neuroblastoma (NB) is the most common solid, extracranial childhood tumor. "After LRP8‐deficient neuroblastomas were established (seven days of postimplantation with five days of Lip‐1 treatment), mice were randomized into two groups." (PMID 37435859, 2023). "Briefly, all cells were grown in the presence of liproxstatin‐1 (Lip‐1) before implantation to prevent ferroptotic cell death of LRP8‐deficient neuroblastoma cells." (PMID 37435859, 2023). "Altogether, our data suggest that low expression of system Xc− components that limit intracellular uptake of inorganic selenium is the likely cause for the remarkable dependence of neuroblastoma cells on LRP8." (PMID 37435859, 2023). "The Trump research team identified LRP8, a low-density lipoprotein receptor, as a critical inhibitor of ferroptosis in MYCN-amplified neuroblastoma, with its regulatory mechanism potentially linked to selenocysteine metabolism." (PMID 40108662, 2025). "Deletion of LRP8 in neuroblastoma cells leads to ferroptosis as a result of an insufficient supply of selenocysteine required for GPX4 biosynthesis (see chapter 2.2.4)." (PMID 38908072, 2024). "Publicly available data (depmap portal) indicate that in neuroblastomas, LRP8 dependency is inversely correlated with SLC7A11 expression with LRP8 knockout sensitive cell lines exhibiting lower SLC7A11 expression levels, while this is not observed for GPX4." (PMID 37435859, 2023). "More clinically relevant, we explored the therapeutic potential of targeting LRP8 in established SK‐N‐DZ neuroblastoma." (PMID 37435859, 2023). "The identification of LRP8 as a specific vulnerability of MYCN‐amplified neuroblastoma cells was confirmed in constitutive and inducible LRP8 knockout orthotopic xenografts." (PMID 37435859, 2023). "We find that the LRP8 dependency in MYCN‐amplified neuroblastomas is partially due to the limited activity of alternative selenium transporters, specifically system Xc−." (PMID 37435859, 2023). "Our observation that MYCN‐amplified neuroblastoma cells are highly dependent on LRP8 for selenium uptake is unanticipated, given that alternative forms and uptake mechanisms exist." (PMID 37435859, 2023). "The low‐density lipoprotein receptor (LRP8) was identified as a critical suppressor of ferroptosis in MYCN‐amplified neuroblastoma." (PMID 37435859, 2023). "LRP8 is a selenoprotein P receptor that is important for protecting MYCN-amplified neuroblastoma." (PMID 38725484, 2024). "Of note, our study shows that forced expression of SLC7A11 prevents cell death of LRP8‐deficient neuroblastoma, but it also demonstrates its negative impact on the survival of these cells." (PMID 37435859, 2023). "Our data also imply that the striking LRP8 dependency may have emerged during tumor evolution as a result of the growth advantage of MYCN‐amplified neuroblastoma displaying low expression/activity of system Xc−." (PMID 37435859, 2023). "Therefore, additional studies on the inhibition of LRP8 in immunocompetent models are warranted to fully understand the therapeutic potential of targeting the LRP8/SELENOP axis for therapeutic benefit in neuroblastoma and other malignancies in particular the ones with amplified MYCN." (PMID 37435859, 2023). "Beside xCT, the SELENOP receptor, LRP8, is required to protect MYCN-amplified neuroblastoma cells from ferroptosis." (PMID 38908072, 2024). "Using CRISPR‐activation screens in ferroptosis hypersensitive cells, we identify the selenoprotein P (SELENOP) receptor, LRP8, as a key determinant protecting MYCN‐amplified neuroblastoma cells from ferroptosis." (PMID 37435859, 2023). "The data above support the requirement of LRP8 for the establishment and maintenance of MYCN‐amplified SK‐N‐DZ neuroblastoma by preventing ferroptosis." (PMID 37435859, 2023).
neuroblastoma (continued). "Our data demonstrate that targeting SELENOP uptake via LRP8 is a valuable strategy to efficiently disrupt GPX4 maintenance and trigger ferroptosis in cultured MYCN‐amplified neuroblastoma cells." (PMID 37435859, 2023). "Using CRISPR/Cas9, LRP8 has been genetically deleted, resulting in the depletion of selenocysteine required for translation of anti-ferroptosis GPX4 and making MYCN-amplified neuroblastoma vulnerable to cell death." (PMID 38725484, 2024). "These additional models recapitulated the observation that LRP8 is essential to support the viability of human neuroblastoma cell lines and that it is also crucial in a cell line derived from a MYCN‐driven genetic neuroblastoma model." (PMID 37435859, 2023). "Their findings demonstrated that inhibiting the SELENOP/LRP8 axis represents a novel and selective strategy to trigger ferroptosis, thereby limiting the growth of highly aggressive and treatment-resistant MYCN-amplified neuroblastoma cells, confirming LRP8 as a promising therapeutic target." (PMID 40108662, 2025). "Thus, LRP8 blockade represents a rational strategy to indirectly deplete GPX4 and selectively trigger ferroptosis in MYCN‐amplified neuroblastoma and potentially other entities with low system Xc− expression/activity such as AML and lymphoma, while sparring normal cells." (PMID 37435859, 2023). "Given the critical role played by LRP8 and the selenocysteine metabolism in preventing ferroptosis in highly aggressive neuroblastoma subtypes with MYCN amplifications, we addressed whether LRP8 elimination could target neuroblastoma growth by inducing ferroptosis in vivo." (PMID 37435859, 2023). "To further corroborate this observation and provide mechanical support for targeting LRP8 in neuroblastoma, we deleted Lrp8 in the murine TH‐MYCN neuroblastoma mouse model and a panel of neuroblastoma cell lines with and without MYCN amplification." (PMID 37435859, 2023).
pancreatic cancer (5 papers, 2016 to 2025). "It has been reported that LRP8 is elevated in pancreatic tumors, and ApoE2-LRP8 facilitates cell cycle function to promote PC cell proliferation via ERK/c-Myc/p21Waf1 signaling." (PMID 39972392, 2025).
triple-negative breast carcinoma (5 papers, 2016 to 2025). An invasive breast carcinoma which is negative for expression of estrogen receptor (ER), progesterone receptor (PR), and human epidermal growth factor receptor 2 (HER2). "Functional studies demonstrated that LRP8 knockdown significantly inhibited proliferation, migration, and invasion of triple-negative breast cancer (TNBC) cells both in vitro and in vivo." (PMID 40506610, 2025). "LRP8 has only been recently identified as a potential target in triple-negative breast cancer and is not currently, to our knowledge, considered for ADC development." (PMID 26700623, 2016).
autism (4 papers, 2016 to 2023). Persistent deficits in social interaction and communication and interaction as well as a markedly restricted repertoire of activity and interest as well as repetitive patterns of behavior. "In a screen of 135 genes in the adult mouse (selected for high cerebellar expression or prior association with autism), we identified only three (Abhd3, Lrp8, and Plcβ4) with a somewhat similar lobular expression pattern to Spry3, and none that recapitulated the p75NTR expression pattern." (PMID 31275178, 2019).
osteosarcoma (4 papers, 2022 to 2025). A usually aggressive malignant bone-forming mesenchymal neoplasm, predominantly affecting adolescents and young adults. "Experimental evidence has shown that reducing the level of LRP8 can promote apoptosis in osteosarcoma and inhibit the unlimited proliferation of osteosarcoma cells." (PMID 38800967, 2024). "In fact, LRP8 is overexpressed in different cancers including osteosarcoma and NSCLC, and its overexpression has been significantly correlated with poor clinicopathological features and prognosis." (PMID 36012187, 2022). "LRP8 has been implicated in various malignancies, with studies showing that its overexpression increases phospho-STAT3 (p-STAT3) levels, a marker associated with metastasis and poorer outcomes in osteosarcoma." (PMID 40506610, 2025). "Research has found that LRP8 have a high expression level in osteosarcoma and activates STAT3 which can promote the expression of PD‐L1 in osteosarcoma." (PMID 38800967, 2024).
psychosis (4 papers, 2019 to 2023). "We also found that the LRP8 variant p.Arg952Gln (rs5174), which was included in the BD-PRS, shows a high functional impact, and it has previously been associated with psychosis." (PMID 33557049, 2021).
antiphospholipid syndrome (3 papers, 2010 to 2024). A disorder caused by the presence of autoantibodies directed against phospholipids, causing a hypercoaguable state, which may result in blood clots, stroke, heart attack, and in women, significant pregnancy-related complications, including miscarriage and still birth. "Furthermore, anti-ß2-glyocprotein I binding to LRP8 in lipid rafts can decrease phospho-eNOS and NO, suggesting that LRP8 signaling could be a potential mechanism for impaired endothelial function in lupus as well as antiphospholipid syndrome (APS)." (PMID 39234308, 2024).
colorectal cancer (3 papers, 2019 to 2021). A primary or metastatic malignant neoplasm that affects the colon or rectum. "Besides, Presenilin1 also cleaves another type 1 transmembrane protein such as Alcadein α, Deleted in colorectal cancer (DCC), LDL receptor family (LRP1 and LRP8), p75-neurotrophin receptor (p75NTR), NOTCH receptor." (PMID 34781973, 2021).
diabetes (3 papers, 2017 to 2025). "However, the Lrp8Δexon19 mice displayed exaggerated insulin resistance and glucose intolerance in response to Western diet feeding, thus indicating that apoER2 exon 19 is necessary to prevent accelerated diabetes onset." (PMID 40722764, 2025).
hepatocellular carcinoma (3 papers, 2022 to 2024). A malignant tumor that arises from hepatocytes. "Corroborating this possibility, generated LRP8 KO breast and hepatocellular carcinoma cell lines presented reduced GPX4 levels, with concomitant reduction of Se levels that caused disruption in the GPX4 translation process." (PMID 36358931, 2022). "Increased expression of LRP8, a low-density lipoprotein receptor that also functions as a receptor for selenoprotein P (SELENOP), was identified to promote ferroptosis resistance in breast cancer and hepatocellular carcinoma cell lines." (PMID 36358931, 2022).
prostate carcinoma (3 papers, 2022 to 2025). A carcinoma that arises from epithelial cells of the prostate gland. "A similar LRP8 regulation by miR-455-5p has been reported by Arai at al. in prostate cancer." (PMID 36012187, 2022).
amyloidosis (2 papers, 2022 to 2024). A disorder characterized by the localized or diffuse accumulation of amyloid protein in various anatomic sites. "Three, can amyloidosis and cell proliferation in cancer be reversed targeting ApoE/LRP8?" (PMID 36012187, 2022). "There is therefore a link between ApoE and Aβ that does not depend on their direct interaction but rather on the ability of the different isoforms of ApoE to modify the processing of APP through LRP8, thus representing a bidirectional bridge between cholesterol metabolism and amyloidosis." (PMID 36012187, 2022).
asthma (2 papers, 2025). "LRP8, through its influence on the Wnt signaling pathway, may contribute to the pathogenesis of asthma, including airway inflammation and remodeling, by interacting with specific Wnt ligands in various cell types." (PMID 40443529, 2025).
breast tumor (2 papers, 2019 to 2020). "The function of LRP8/ApoER2, strongly expressed in ER negative breast tumors was recently described in breast tumor initiating cells, which constitute a clinical challenge of the pathology." (PMID 32850302, 2020). "We found that low‐density lipoprotein receptor‐related protein 8 (LRP8) was more strongly expressed in estrogen receptor‐negative breast tumors, including TNBCs and those overexpressing HER2, than in luminal breast tumors and normal breast tissues." (PMID 30575334, 2019). "We show for the first time that LRP8 RNA levels were higher in estrogen‐negative breast tumors (TNBC and HER2 [ER−/HER2+] tumors), than in luminal breast tumors (LA [ER+/HER2−] and LB [ER+/HER2+] samples), and that these levels were the highest in TNBC samples, in three different cohorts." (PMID 30575334, 2019).
Colon Cancer (2 papers, 2022). "Numerous studies have demonstrated that the Wnt/β-catenin signaling pathway is responsible for the migration and metastasis of cancer cells, mediated by the estrogen receptor/NOD-like receptor-LRP8 axis in colon cancer." (PMID 35246020, 2022).
Hypercholesterolemia (2 papers, 2024 to 2025). An increased concentration of cholesterol in the blood. "In particular, apoER2 plays an important role in limiting denudation injury-induced neointima formation in the vessel wall, and the absence of apoER2 in Lrp8−/− mice accelerates the hypercholesterolemia-induced progression of atherosclerotic plaques to a more complex necrotic lesion." (PMID 40722764, 2025).
Hyperglycemia (2 papers, 2025). An increased concentration of glucose in the blood. "In contrast, Lrp8−/− mice fed a high-fat–high-cholesterol Western-type diet displayed lower adiposity with slower development of hyperinsulinemia but accelerated onset of hyperglycemia." (PMID 40722764, 2025).
Infertility (2 papers, 2022 to 2025). "This gene is a component of the selenium delivery pathway to spermatogenic cells of mice, LRP8 deficiency causes infertility in male mice, and it is necessary for sperm maturation." (PMID 35456401, 2022).
leukemia (2 papers, 2016 to 2021). A malignant (clonal) hematologic disorder, involving hematopoietic stem cells and characterized by the presence of primitive or atypical myeloid or lymphoid cells in the bone marrow and the blood. "LRP8, an indicator of poorer prognosis was highly expressed in metastatic TNBC cells according to scRNA-seq data, and its ligand LRPAP1 was reported to induce T-cell proliferation in leukemia." (PMID 34611125, 2021). "Furthermore, we also identified a strong correlation in ETV6/RUNX1-positive leukemias between NETO1 and its adjacent, bidirectional lncRNA lnc-TIMM21-5 (r = 0.89) as well as between LRP8 and lnc-CPT2-7 (r = 0.70)." (PMID 27650541, 2016).
mental disorder (2 papers, 2014 to 2023). A disease that has its basis in the disruption of mental process. "Overall, pleiotropic variants between gastrointestinal tract diseases and psychiatric disorders were extensively distributed, with several loci especially highlighted between certain trait pairs, such as 1q32.1 (INAVA), 19q13.33 (FUT2), 11q23.2 (NCAM1), and 1p32.3 (LRP8)." (PMID 36753304, 2023).
aneurysm (1 paper, 2020). Bulging or ballooning in an area of an artery secondary to arterial wall weakening. "Macroscopic inspections of aortas from AngII infused mice revealed massive aortic dissections in three of the LRP8−/− mice that died prematurely, and an aneurysm in one mouse that died in both the LRP8+/+ and LRP8−/− group." (PMID 32664652, 2020). "In patients with aortic dissection independent of the presence of an aneurysm, lipoprotein(a) was elevated compared to control subjects, but to date no direct relations between LRP8 genetic variants and aneurysm or aortic dissection have been reported." (PMID 32664652, 2020).
Aortic dissection (1 paper, 2020). Aortic dissection refers to a tear in the intimal layer of the aorta causing a separation between the intima and the medial layers of the aorta. "Contrary to other models of aortic dissections with lower rates of death, AngII-infused LRP8 deficient mice have high mortality rates, reflecting the lethality of aortic dissection in human medicine." (PMID 32664652, 2020). "We observed that blood pressure, assessed by tail cuff measurements, was not significantly increased in LRP8 deficient mice infused with AngII, which may be compatible with aortic dissection complicated by malperfusion syndrome or distributive shock with hypotension." (PMID 32664652, 2020). "In human physiopathology, a direct role of LRP8 in the development of aortic dissection has not yet been demonstrated." (PMID 32664652, 2020).
bone sarcoma (1 paper, 2015). A sarcoma that arises from the bone. "LRP6, LRP8 and Ror2 levels were significantly higher in bone sarcoma cells than in hMSC, while LRP5 levels were decreased in bone sarcoma cells." (PMID 25999350, 2015).
colon adenocarcinoma (1 paper, 2022). "Apolipoprotein E receptor 2 (ApoER2 or LRP8) is a reelin receptor that downregulates reelin expression, and we found a negative correlation between the expression of this receptor and that of reelin in human colon adenocarcinoma." (PMID 36290310, 2022).
Ewing sarcoma (1 paper, 2023). A small round cell tumor that lacks morphologic, immunohistochemical, and electron microscopic evidence of neuroectodermal differentiation. "A recently published cancer dependency map of pediatric tumors identified LRP8 as an essential gene in pediatric Ewing sarcoma and medulloblastoma, all entities associated with MYCN amplifications." (PMID 37435859, 2023).
ischemia (1 paper, 2025). A hypoperfusion of the BLOOD through an organ or tissue caused by a PATHOLOGIC CONSTRICTION or obstruction of its BLOOD VESSELS, or an absence of BLOOD CIRCULATION. "LRP8 expression was significantly reduced in CA1 at later times post-ischemia." (PMID 41091415, 2025).
Learning disabilities (1 paper, 2019). "For example, in a mouse model of genetically manipulated inhibition of the Reelin/LRP8 signaling pathway, mice demonstrated marked fear-conditioning deficits and Learning disabilities." (PMID 30622122, 2019).